RNU6-442P (RNA, U6 small nuclear 442, pseudogene)
Gene: Small nuclear RNA gene on chromosome 8 (125,900,951 to 125,901,054, forward strand). Ensembl gene ENSG00000206695.
Homologues: Orthologues: chimpanzee U6 (99% identical), macaque U6 (90% identical), guinea pig U6 (84% identical), rabbit U6 (81% identical), dog U6 (76% identical), mouse Gm24646 (76% identical), mouse Gm24905 (70% identical). Paralogues in human: RNU6-45P (86% identical), RNU6-1075P (85% identical), RNU6-1145P (85% identical), RNU6-1316P (85% identical), RNU6-393P (85% identical), RNU6-41P (85% identical), RNU6-44P (85% identical), RNU6-589P (85% identical), RNU6-1152P (84% identical), RNU6-35P (84% identical), RNU6-39P (84% identical), RNU6-434P (84% identical), and 1285 more.